SIRT2 (sirtuin 2)
Diseases named in the same sentence as SIRT2 in open-access papers (continued):
Sharing a sentence is not in itself a finding about the gene and the disease.
Salmonella Infections (4 papers, 2018 to 2024). Infections with bacteria of the genus SALMONELLA. "We find that CDC42 K153 can be deacetylated by the NAD+-dependent deacetylase SIRT2 after Salmonella infection, which causes an impaired binding of its downstream effector PAK4." (PMID 36812247, 2023). "Salmonella infection activates SIRT2 to deacetylate CDC42 K153, reduces cell apoptosis, enhances the migration and invasion abilities of tumor cells, and promotes tumorigenesis." (PMID 36812247, 2023). "Although, SIRT2-/- mice survives longer than wild type mice in response to Salmonella infection, eventually, these mice succumb to the infection." (PMID 30452468, 2018). "During Salmonella infection ex vivo, SIRT2 regulates two opposing phenomena namely, intracellular bacterial clearance and suppression of T cell proliferation." (PMID 30452468, 2018). "Overall, the current study suggests, inhibition of SIRT2 during Salmonella infection shows a protective role in vivo." (PMID 30452468, 2018). "Previous reports have elucidated the role of SIRT1 and SIRT2 pertaining to Salmonella infection." (PMID 39693143, 2024). "In summary, we found that Salmonella infection decreased the acetylation level of CDC42 K153 through SIRT2, and the low acetylation level of CDC42 K153 could block the interaction between CDC42 and PAK4." (PMID 36812247, 2023). "The qPCR results demonstrate that Salmonella infection upregulates SIRT2 mRNA." (PMID 30452468, 2018). "Salmonella infection results in upregulation of SIRT2 in DCs." (PMID 30452468, 2018). "Both isoforms of SIRT2 are upregulated in response to Salmonella infection at protein level." (PMID 30452468, 2018). "Salmonella infection results in upregulation of SIRT2 in DCs at 20 h post- infection." (PMID 30452468, 2018). "In this study, we have demonstrated that Salmonella infection upregulates SIRT2 expression in DCs." (PMID 30452468, 2018). "In HEK293T cells with stable knockdown of SIRT2, Salmonella infection failed to reduce K153 acetylation and the binding of CDC42 to PAK4 was restored." (PMID 36812247, 2023). "Although, various previous studies have focused on the role of host epigenetic modification during Salmonella pathogenesis, till date, there has been no study on the role of SIRT2 in Salmonella infection." (PMID 30452468, 2018). "Additionally, SIRT2-/- DCs show no significant increase in nitric oxide level in response to Salmonella infection." (PMID 30452468, 2018).
staphylococcal infection (4 papers, 2017 to 2021). An infection caused by Staphylococcus. "SIRT2 deficiency was also shown to promote phagocytosis by macrophages leading to increased survival of mice with chronic staphylococcal infection." (PMID 34155309, 2021). "SIRT2-/- mice show prolonged survival and better bacterial clearance as compared to wild type mice in chronic staphylococcal infection." (PMID 30452468, 2018). "SIRT2 deficiency protects from chronic staphylococcal infection, while having no impact on toxic shock, endotoxemia, fulminant peritonitis, non-lethal pneumonia, and chronic candidiasis." (PMID 28894448, 2017). "Additionally, SIRT2 deficiency did not influence the development of chronic candidiasis as it did for chronic staphylococcal infection." (PMID 28894448, 2017).
synucleinopathies (4 papers, 2017 to 2023). "In relation with the role of α-Syn acetylation, it has been also found that SIRT2 removes acetyl groups from α-Syn, while the inhibition of SIRT2 decreases α-Syn toxicity in in vitro and in vivo models of synucleinopathy." (PMID 37686236, 2023). "Due to acetylation induces a reduction in α-synuclein oligomerization and aggregation, and SIRT2 interacts with alpha-synuclein leading to its deacetylation, SIRT2 inhibition has been proposed as a potential therapeutics against synucleinopathies." (PMID 36755296, 2023). "Our study identifies α-synuclein acetylation as a key regulatory mechanism governing α-synuclein aggregation and toxicity, demonstrating the potential therapeutic value of sirtuin 2 inhibition in synucleinopathies." (PMID 28257421, 2017). "Here, we provide mechanistic insight into the interplay between sirtuin 2 and α-synuclein, the major component of the pathognomonic protein inclusions in PD and other synucleinopathies." (PMID 28257421, 2017). "In the present study, we provide strong evidence demonstrating that SIRT2 inhibition robustly alleviates neuropathology in several models of synucleinopathy by regulating the levels of aSyn acetylation." (PMID 28257421, 2017). "Accordingly, SIRT2 inhibition or genetic deletion rescued α-synuclein toxicity and showed neuroprotective effects in different in vitro and in vivo models of PD, demonstrating the potential therapeutic value of SIRT2 inhibition in synucleinopathies and, more specifically, in PD." (PMID 38132302, 2023).
asthma (3 papers, 2022 to 2023). "SIRT2 (Sirtuin 2) is a NAD-dependent histone deacetylase that is involved in the pathogenesis of asthma." (PMID 38041162, 2023). "SIRT2 was still upregulated at revisit after 3 months, which could be important for the development of allergic sensitization and asthma." (PMID 38006384, 2023). "Pharmacological inhibition of SIRT2 with the specific inhibitor prevents OVA-induced lung fibrosis and inflammatory response in asthma." (PMID 38041162, 2023). "Collectively, our results suggest that SYVN1 promotes SIRT2 ubiquitination and induces inactivation of ER stress, which blocks EMT process and attenuates airway remodeling in asthma." (PMID 38041162, 2023). "In addition to SIRT1, SIRT2, SIRT3, SIRT6, and SIRT7 have also been reported to be involved in asthma." (PMID 36581622, 2022).
bladder cancer (3 papers, 2019 to 2026). "Tubacin administration at micro-molar concentrations, combined with the siRNA-mediated knockout of SIRT2, caused the suppression of cell migration and invasion, thus indicating tubacin as a promising therapeutic agent for bladder cancer therapy." (PMID 30875794, 2019). "Because SIRT2 has also been suggested to be involved in cortactin deacetylation in A549 cells and work synergistically with HDAC6 to promote cell migration and invasion in bladder cancer, we examined the role of SIRT2 in dendrite development in vitro." (PMID 32711564, 2020). "HDAC6 has been previously shown to act synergistically with SIRT2, in promoting bladder cancer-cell migration and invasion, by targeting the cytoskeletal protein Cortactin in the cell line BLX211." (PMID 30875794, 2019).
Burkitt lymphoma (3 papers, 2012 to 2020). A rare form of malignant mature B-cell non-Hodgkin lymphoma. "Intriguingly, a follow-up study with cambinol-based dual SIRT1/2 inhibitors demonstrated a strong correlation between SIRT2 inhibitory activity and cytotoxicity in Namalwa Burkitt lymphoma cell line." (PMID 31973227, 2020). "With selective SIRT2 inhibitors in hand, we proceeded to evaluate cytotoxicity of our compounds in Daudi, Raji (Burkitt lymphoma) and OCI-Ly8-LAM-53 (OCI, a representative of several Diffuse Large B-Cell Lymphoma lines; DLBCL) cell lines." (PMID 31973227, 2020). "Cambinol, an inhibitor of SIRT1 and SIRT2, promotes apoptosis Burkitt lymphoma xenografts in mice." (PMID 22275802, 2012). "Additionally, SIRT2 inhibition has been shown to exert an anti-proliferative effect by facilitating degradation of c-myc; the oncogene which is constitutively active in several Burkitt lymphomas." (PMID 31973227, 2020). "Interestingly, treatment of BCL6-expressing Burkitt lymphoma cells and Burkitt lymphoma xenograft mice with a dual SIRT1 and SIRT2 inhibitor, cambinol, produced a potent antitumor effect." (PMID 24259290, 2013). "Previously, we described the discovery of a dual SIRT1/SIRT2 inhibitor called cambinol (IC50 56 and 59 μM, respectively), which showed cytotoxic activity against cancer cells in vitro and a marked anti-proliferative effect in a Burkitt lymphoma mouse xenograft model." (PMID 31973227, 2020).
cholangiocarcinoma (3 papers, 2020 to 2022). A carcinoma that arises from the intrahepatic biliary tree (intrahepatic cholangiocarcinoma) or from the junction, or adjacent to the junction, of the right and left hepatic ducts (hilar cholangiocarcinoma). "Sirt2 reduces oxidative stress-induced apoptosis by influencing the cMYC (a transcription factor) pathway in cholangiocarcinoma." (PMID 34903175, 2021). "In cholangiocarcinoma, SIRT2 induces Warburg-like metabolic reprogramming resulting in decreased oxidative phosphorylation and increased activity of the serine synthesis pathway, consequently protecting cholangiocarcinoma cells from oxidative stress and apoptosis." (PMID 32117717, 2020). "The SIRT2/cMYC pathway is involved in the conversion of glucose oxidative metabolism to serine anabolic metabolism in cholangiocarcinoma (CCA)." (PMID 35915188, 2022).
dementia (3 papers, 2021 to 2023). Loss of intellectual abilities interfering with an individual's social and occupational functions. "Past studies have found SIRT2 to be highly expressed in the temporal cortex of individuals with associated dementia (AD)." (PMID 36719240, 2023). "We therefore analyzed SIRT1 and SIRT2 expression in buffy coat samples from healthy subjects and patients with dementia." (PMID 35008438, 2021).
diabetic cardiomyopathy (3 papers, 2021 to 2025). Diabetic cardiomyopathy is a disorder of the heart muscle in people with diabetes. "Considering that the roles of SIRT3 and SIRT5 in diabetic cardiomyopathy have been validated 23, 28, we assessed the expression patterns of SIRT2 and SIRT4 in heart tissues." (PMID 39781464, 2025). "At present, there are very few direct studies on the relationship between SIRT2 and diabetic cardiomyopathy." (PMID 34028177, 2021). "SIRT2 can reduce the content of ROS, which provides another idea for the treatment of diabetic cardiomyopathy." (PMID 34028177, 2021). "Notably, our study aimed to elucidate the pivotal role of SIRT2 in the pathogenesis of diabetic cardiomyopathy, which is characterized by distinct alterations in cardiac energy metabolism." (PMID 39781464, 2025). "Collectively, our results demonstrate that cardiac mitochondrial SIRT2 could serve as a potential therapeutic target for diabetic cardiomyopathy and related metabolic disorders." (PMID 39781464, 2025). "SIRT2 can reduce the level of reactive oxygen species (ROS), which may help to reduce the severity of diabetic cardiomyopathy." (PMID 34028177, 2021).
fibromyalgia (3 papers, 2022 to 2025). A chronic disorder of unknown etiology characterized by pain, stiffness, and tenderness in the muscles of neck, shoulders, back, hips, arms, and legs. "Similarly, AXIN1 and SIRT2 are linked to immune regulation and cellular stress and have been linked to the severity of pain, fatigue, and some other symptoms in fibromyalgia." (PMID 39996743, 2025). "Moreover, increased levels of inflammatory serum proteins, including IL-8, IL-37, AXIN1, and SIRT2, have been identified through proteomics and ELISA as correlates of fibromyalgia symptom severity." (PMID 39996743, 2025). "The top five proteins that distinguished fibromyalgia patients from plasma controls were in serum STAMBP, SIRT2, CD40, AXIN1 and IL-7 and in CSF (CCL19, CCL23, IL-18, CX3CL1, FGF19, CXCL10, CCL11)." (PMID 36327322, 2022).
head and neck cancer (3 papers, 2021 to 2022). A primary or metastatic malignant neoplasm affecting the head and neck. "The expression levels of SIRT2 in head and neck cancer were upregulated in five unique analyses and downregulated in one unique analysis." (PMID 35136826, 2022).
Hyperinsulinemia (3 papers, 2018 to 2024). An increased concentration of insulin in the blood. "Hepatic Sirt2 knockdown caused a slight increase in the blood glucose level and clear hyperinsulinemia under ad libitum feeding." (PMID 29296001, 2018). "Watanabe reported that Sirt2 downregulation resulted in a slight increase in blood glucose levels and significant hyperinsulinemia." (PMID 39004743, 2024). "Nevertheless, this discrepancy may be attributed to hyperinsulinemia as well as SIRT2 inhibition by nicotinamide." (PMID 34948019, 2021).
ischemia (3 papers, 2020 to 2023). A hypoperfusion of the BLOOD through an organ or tissue caused by a PATHOLOGIC CONSTRICTION or obstruction of its BLOOD VESSELS, or an absence of BLOOD CIRCULATION. "In addition, expression levels of nicotinamide adenine dinucleotide (NAD)-dependent protein deacetylase sirtuin-2 (SIRT2) was significantly increased in DG after ischemia, but decreased in CA1." (PMID 33041514, 2020). "Thus, the growth of SIRT1 and SIRT2 levels in neurons and of SIRT1 in astrocytes of penumbra, as well as the redistribution of SIRT1 to neuronal cytoplasm, undoubtedly indicate the involvement of these sirtuins in the response of brain cells to ischemia." (PMID 35574497, 2022).
liver diseases (3 papers, 2021 to 2024). "SIRT2 has been implicated in the aging process and liver diseases." (PMID 37188819, 2023). "Overall, this effect of SIRT1 and SIRT2 in liver diseases including NAFLD, has been observed to be similar." (PMID 38993557, 2024).
metastatic melanoma (3 papers, 2019 to 2021). A melanoma that has spread from its primary site to another anatomic site. "Next, we analyzed the effects of pharmacological inhibition of sirtuin 2 on cisplatin activity against a metastatic melanoma cell line with intact sirtuin 2 expression." (PMID 34068624, 2021). "We chose the WM853 line, representing the primary/vertical growth stage and MDA-MD-435S representing metastatic melanoma as previous studies indicated that the role of SIRT2 might change with the advancement of cancer development." (PMID 31091806, 2019).
Nephropathy (3 papers, 2022 to 2025). A nonspecific term referring to disease or damage of the kidneys. "Its cross-sectional design prevents conclusions about causality, making it uncertain whether elevated SIRT2 actively contributes to the development of nephropathy or simply reflects existing renal injury." (PMID 41303131, 2025). "In addition to SIRT2, several classical clinical and biochemical parameters differed significantly among the three groups, further supporting the validity of our cohort and highlighting established risk factors for nephropathy." (PMID 41303131, 2025). "Further, the present data revealed two alternatively spliced genes, namely Sirtuin 2 (SIRT2) and Heat Shock Transcription Factor 1 (HSF1) entangled in response to oxidative stress, encoding factors that are activated for instance in kidney damage." (PMID 38074096, 2023). "Importantly, in this comparison, high SIRT2 values identified nephropathy patients with 100% specificity, indicating that markedly elevated concentrations strongly predict the presence of advanced disease." (PMID 41303131, 2025). "At a cut-off value of 8.2 ng/mL, SIRT2 achieved 75% sensitivity and 78% specificity, showing that it can reliably discriminate nephropathy from non-diabetic individuals." (PMID 41303131, 2025). "Overall, our findings do not entirely refute the role of the SIRT1 and SIRT2 pathways in DN disorders, but offer insights into the pathophysiological roles of SIRT1 and SIRT2 in nephropathy." (PMID 36139886, 2022).
non-alcoholic fatty liver disease (3 papers, 2024 to 2025). "In the liver, SIRT2 regulates liver fibrosis by affecting hepatic stellate cell's activation, HBV replication, transcription, and non-alcoholic fatty liver disease." (PMID 39226168, 2024).
osteosarcoma (3 papers, 2021 to 2024). A usually aggressive malignant bone-forming mesenchymal neoplasm, predominantly affecting adolescents and young adults. "In this study, we identified the oncogenic role of SIRT2 in osteosarcoma and explored the underlying molecular mechanism of SIRT2 in the invasion and metastasis of osteosarcoma cells through in vivo and in vitro experiments." (PMID 36344502, 2022). "Knockdown of Snail abrogated the promoting effects of SIRT2 on migration and invasion of osteosarcoma cells." (PMID 36344502, 2022). "A xenograft mouse model showed that SIRT2 knockdown in osteosarcoma cells led to reduced tumor growth, decreased expression of mesenchymal markers and impaired lung and liver metastasis in vivo." (PMID 36344502, 2022). "Our results showed that the overexpression of SIRT2 greatly increased the viability, migration and invasion of osteosarcoma cells." (PMID 36344502, 2022). "SIRT2 knockdown inhibited both tumorigenesis and lung and liver metastasis of osteosarcoma via Snail in vivo." (PMID 36344502, 2022). "In this study, we confirmed that SIRT2 was highly-expressed in human osteosarcoma MG63 and Saos-2 cell lines." (PMID 36344502, 2022). "In summary, SIRT2 is increased in osteosarcoma cells and promotes the viability, migration and invasion of osteosarcoma cells." (PMID 36344502, 2022). "We infected MG63 cells with SIRT2 shRNA lentivirus and established an osteosarcoma cell line with stable SIRT2 knockdown (MG63-shSIRT2)." (PMID 36344502, 2022). "We proved the binding of SIRT2 and Snail in osteosarcoma cells and showed that SIRT2 positively regulated the expression of Snail." (PMID 36344502, 2022). "Since SIRT2 is highly expressed in osteosarcoma cell lines MG63 and Saos-2, two small interfering RNAs (siRNAs) of SIRT2, Si-SIRT2-1 (abbreviated as Si-1) and Si-SIRT2-2 (abbreviated as Si-2) were used to transfect MG63 and Saos-2 cells respectively." (PMID 36344502, 2022). "In this study, we aimed to explore the role of SIRT2 in the development and migration of osteosarcoma, which to date has remained unclear." (PMID 36344502, 2022). "The results of Transwell assay showed that the number of cells passing through the chamber was decreased after SIRT2 knockdown, indicating that SIRT2 knockdown inhibited the migration and invasion of osteosarcoma cells." (PMID 36344502, 2022). "The expression level of SIRT2 in osteosarcoma U2OS cells was relatively low, so the pENTER-SIRT2-c-Flag-His plasmid was transfected into U2OS cells." (PMID 36344502, 2022). "The viability, migration and invasion of osteosarcoma cells were inhibited by knockdown of SIRT2 and were enhanced by overexpression of SIRT2." (PMID 36344502, 2022). "The CCK-8 assay showed that SIRT2 knockdown inhibited the viability of osteosarcoma cells." (PMID 36344502, 2022). "In addition, knockdown of SIRT2 inhibited osteosarcoma cell viability, migration and invasion, while overexpression of SIRT2 promoted osteosarcoma cell viability, migration and invasion." (PMID 36344502, 2022). "In this study, SIRT2 showed increased levels in the osteosarcoma cell lines MG63 and Saos-2." (PMID 36344502, 2022). "The mRNA level of SIRT2 was also significantly increased in osteosarcoma MG63 and Saos-2 cells." (PMID 36344502, 2022). "Thus, we focused on SIRT1 and SIRT2 in this study and detected the expression of these two proteins in hFOB1.19 (human osteoblasts) and several osteosarcoma cell lines MG63, HOS, U2OS and Saos-2." (PMID 36344502, 2022). "In conclusion, SIRT2 plays a crucial role in osteosarcoma metastasis by inhibiting Snail degradation and may serve as a novel therapeutic target to manage osteosarcoma." (PMID 36344502, 2022). "The results showed that the volume and weight of tumors in the SIRT2 knockdown group were significantly lower than those in the control group, indicating that SIRT2 knockdown inhibited the proliferation of osteosarcoma cells in nude mice." (PMID 36344502, 2022).